TNF (tumor necrosis factor)
Diseases named in the same sentence as TNF in open-access papers (continued):
Sharing a sentence is not in itself a finding about the gene and the disease.
tumor (continued). "Nuclear translocation of NF−κB subunits (p65/p50) induces transcription of pro-inflammatory cytokines (IL−1β, IL−12, TNF-α) that sustain anti-tumor immunity." (PMID 40936918, 2025). "Previous studies have demonstrated that Fib can activate monocytes to secrete proinflammatory cytokines such as tumor necrosis factor-α (TNF-α) and IL-6, thereby promoting tumor cell proliferation and survival." (PMID 41426339, 2025). "Exposure to the pro-inflammatory cytokines IFN-γ, IL-12, and TNF-α has been shown to improve the antigen presenting properties of DCs and enhance the activation and cytolytic function of tumor-infiltrating lymphocytes (TILs)." (PMID 40643499, 2025). "Tumor necrosis factor-α (TNF-α)-induced angiogenesis plays a critical role in tumor progression and metastasis, making it an important therapeutic target in cancer treatment." (PMID 40191430, 2025). "Our findings demonstrate that SFV vectors, particularly those engineered to deliver TNFα or IFNγ, can reprogramme macrophages towards an anti-tumour phenotype, with substantial implications for cancer immunotherapy." (PMID 40547518, 2025). "CD8α:MyD88 T cells exhibited enhanced proliferation, cytokine production (IFN-γ, TNF-α), elevate cytotoxic activity, and increased costimulatory receptor expression, leading to tumor regression in a B16-F1 melanoma model." (PMID 40948803, 2025). "The results indicated a significant increase in the expression of INF-γ and TNF-α in the tumor tissues of mice from the sh-LOX, sh-LOXL1, sh-LOXL2, sh-LOXL3, and sh-LOXL4 groups compared to the sh-NC group." (PMID 40270974, 2025). "TLR7 agonists stimulate immune cells to secrete various cytokines, such as IFN-α and TNF-α, thereby enhancing the body’s anti-tumor capacity." (PMID 41488647, 2025). "Based on this approach, TNF-α, IL-6 and IL-12 showed the highest discriminative ability between tumour and normal tissue (AUC 0.76, 0.65 and 0.65, respectively), while TGF-β1 and IL-1α yielded AUC values close to 0.5, indicating limited diagnostic value." (PMID 41465261, 2025). "Cytotoxic CD8+ T cells recognize tumor cells’ neo-antigens and kill tumor cells, creating perforin and granzyme pores on their membrane and inducing cell apoptosis through the IFNγ and TNF pathways." (PMID 41413686, 2025). "Itis important to note that IFN-γ- or TNF-α-induced ferroptosis candevelop only at the initial stages of the disease; when the tumor switches tothe aggressive growth phase, a shift towards IL-6 secretion occurs." (PMID 40264585, 2025). "For instance, IL-1β and TNF-α signaling through NF-κB can lead to the expression of pro-inflammatory genes that promote tumor cell apoptosis." (PMID 40486614, 2025). "Compared with surgical margins, tumour tissues showed a characteristic inflammatory shift, with markedly increased IL-1β and IL-6 and relatively reduced TNF-α, IFN-γ, IL-12 and IL-2." (PMID 41465261, 2025). "The outcome of TNF-α signaling depends on the tumor’s molecular profile and microenvironmental cues." (PMID 40868199, 2025). "Under normal conditions, TNF is involved in regulating T lymphocyte-mediated homeostasis and anti-tumor responses, thereby improving CR rates and extending event-free survival." (PMID 40861464, 2025). "TNFRSF1B (also known as TNFR2), a receptor for the pro-inflammatory cytokine TNF-α, is primarily expressed in immune cells, endothelial cells, and certain tumor cells, playing a pivotal role in immune regulation, inflammation, and cell survival." (PMID 40547917, 2025). "Cirrhosis‐associated KCs upregulate the expression of FasR on metastatic tumor cells, making them sensitive to FasR‐mediated apoptosis and preparing them for clearance by lymphocytes, potentially mediated by TNF‐α." (PMID 40027151, 2025). "Macrophage-derived TNF-α and IL-1α lead tumor cells to produce potent angiogenic factors IL-8 and VEGF, which affect angiogenesis and tumor growth." (PMID 40658605, 2025).
tumor (continued). "In the colon, LPS and other pathogen-associated molecules activate mucosal immune cells to release pro-inflammatory cytokines (e.g., IL-1β, IL-6, TNF-α), creating an environment conducive to tumor promotion." (PMID 41374093, 2025). "TNF-α recruits immunosuppressive cells, which can inhibit anti-tumor immune responses and enhance tumor cell survival and metastasis." (PMID 40722646, 2025). "TNFRSF1A, one of the receptors for TNF-alpha, supports tumor development by activating NF-kappaB and regulating inflammation." (PMID 40870378, 2025). "Proinflammatory cytosine TNF-α has a wide range of functions both in response to infection, tumor transformation, and in metabolic processes and in the functioning of adipose tissue." (PMID 40647668, 2025). "In vivo, PTE suppressed tumor growth and remodeled the tumor microenvironment by increasing granzyme B+, TNF-α+, and IFN-γ+ CD8+ T cells while reducing myeloid-derived suppressor cells and regulatory T cells." (PMID 41181138, 2025). "By releasing cytokines such as IFN-γ, TNF, and IL-2, CD4+ T cells further promote the differentiation and activation of macrophages, CD8+ T cells, and NK cells, while limiting tumor-associated angiogenesis, thereby reinforcing antitumor responses." (PMID 41320679, 2025). "Conversely, introduction an antisense targeting 5′‐half‐GlyGCC to tumour Te‐EVs abrogated p65 phosphorylation and reduced TNF‐α and IL‐6 secretion in dTHP‐1 cells via TLR8." (PMID 40326665, 2025). "Functional reactivity was evidenced by the upregulation of 4-1BB in CD8+ T cells, OX40 in CD4+ T cells, and increased production of IFN-γ and TNF-α upon autologous tumor stimulation." (PMID 40806287, 2025). "The dual role of TNF-α, in both tumor growth enhancement and suppression complicates its use for therapy." (PMID 40309351, 2025). "Ablation of NR2F6 enhances the expression of interleukin-2 (IL-2), interferon -γ (IFN-γ), and tumor necrosis factor-α (TNF-α) secretion, thereby promoting anti-tumor immune responses." (PMID 40424451, 2025). "This was based on the role of TNF-α in host defense, particularly in infection control and tumor surveillance via natural killer cells and CD8+ lymphocytes." (PMID 41302997, 2025). "Increased regulatory T cells (Tregs) in IAC samples suggested an immunosuppressive trend during tumor progression, potentially regulated by cytokines such as interleukin-6 (IL-6), interleukin-10 (IL-10), and tumor necrosis factor-alpha (TNF-α)." (PMID 41417416, 2025). "On one hand, TNF-α induces cell cycle arrest in ER-positive breast cancer cells at the G0/G1 phase, impeding DNA synthesis and exerting tumor-suppressive effects." (PMID 40909271, 2025). "For example, pro-inflammatory cytokines in the tumor microenvironment (e.g., IL-6, TNF-α, and IL-1β) can activate signaling pathways (e.g., NF-κB and STAT3) that promote tumor cell proliferation, invasive capacity, and resistance to therapy." (PMID 39940440, 2025). "CAR-NK cells also secrete proinflammatory cytokines such as interferon-gamma (IFN-γ) and tumor necrosis factor-alpha (TNF-α), which not only contribute to direct tumor control but also modulate the tumor microenvironment (TME) to enhance antitumor immunity." (PMID 40723278, 2025). "It is induced by IFN-γ, prostaglandin E2, TNFα, TGFβ, and other proinflammatory signals and is expressed by tumour, endothelial and dendritic cells, and macrophages within the tumour microenvironment." (PMID 40430784, 2025). "Tumor cells release several pro-inflammatory and prothrombotic cytokines, such as TNF-α and L-1β, that can trigger prothrombotic processes." (PMID 40944099, 2025). "In cancer, the combination of TNF modulation with immune checkpoint inhibitors is being explored to boost anti-tumor immunity while addressing its role in chronic inflammation and immune tolerance." (PMID 41376630, 2025). "M1 macrophages produce pro-inflammatory cytokines such as INF-γ and TNF-α, which can inhibit tumor growth and promote tumor immunity." (PMID 40895532, 2025).
tumor (continued). "Treated tumor-bearing mice exhibited lowered IL-6 and TNF-α levels and near-normal liver and kidney function, whereas free doxorubicin caused significant inflammation and organ stress." (PMID 40943339, 2025). "Chronic inflammation plays a role as adipose tissue secretes pro‐inflammatory cytokines such as TNF‐α and IL‐6, which promote tumor progression and angiogenesis." (PMID 40387523, 2025). "N1 TANs directly kill tumor cells via cytotoxic agents (H2O2, TNF-α), whereas N2 TANs promote tumor progression by secreting ROS, VEGF, and MMP-9 to induce angiogenesis, matrix degradation, and immunosuppression." (PMID 41459159, 2025). "Depressive mood, by markedly elevating TNF-α levels, hyperactivates NF-κB signaling, thereby shaping an immunosuppressive tumor microenvironment and inducing immune escape, which consequently accelerates cancer progression." (PMID 41000397, 2025). "When class I MHC ligands of NK cell inhibitory receptors are downregulated, which commonly occurs in tumour cells, the loss of inhibitory signals and the resulting unabated positive signalling also leads to NK cell activation (IFN-γ and TNF-α)." (PMID 40421027, 2025). "The macrophages are associated with histologically evident phagocytic clearance of tumor cells which is quite expected due to the concerted action of upregulated immune activating effects of IFNγ and TNFα." (PMID 40560386, 2025). "The M1 phenotype is associated with producing pro-inflammatory cytokines such as tumor TNF-α and IL-1β which are crucial for early pregnancy stages to support tissue remodeling and trophoblast invasion." (PMID 39859499, 2025). "The interaction of platelets with tumor cells through various mechanisms provides protection against TNF-α mediated cytotoxicity, facilitating these cells’ evasion of the immune response and contributing to metastasis." (PMID 40004836, 2025). "Another factor that helps tumor cells to evade the immune system is the immune checkpoint inhibitors expressed by the tumor cells in response to TNF-α." (PMID 40558596, 2025). "For example, BCAAs can activate the NF-κB pathway, leading to the production of cytokines such as interleukin-6 (IL-6) and tumor necrosis factor-alpha (TNF-α), which can support tumor progression and alter immune responses." (PMID 40438606, 2025). "Tumor-derived cytokines, notably IL-6 and tumor necrosis factor α (TNF-α), contribute to adipose tissue inflammation, impairing insulin sensitivity." (PMID 41397158, 2025). "Functionally, ILC1-like NK cells exhibited a higher capacity to secrete cytokines, particularly TNF-α, a cytokine known to promote tumor progression in HCC due to its proinflammatory and proangiogenic properties." (PMID 41268557, 2025). "GASTON-Mix reveals spatial gradients in the striatum and lateral septum that regulate complex social behavior, and GASTON-Mix reveals localized spatial gradients of hypoxia and TNF-α signaling in the tumor microenvironment." (PMID 40662777, 2025). "Conversely, pro-inflammatory cytokines such as IFN-γ and TNF-α drive M1 polarization, enhancing tumor immunity." (PMID 40330466, 2025). "Adipocytes themselves, together with immune cells such as macrophages, regulate the inflammatory status of the adipose‐rich TME by releasing inflammatory factors such as IL‐1, IL‐6 and TNF‐α, all of which benefit tumor progression." (PMID 39496581, 2025). "WC reflects visceral fat, which is metabolically more active than subcutaneous fat and secretes pro-tumorigenic cytokines including leptin, TNF-α, and IL-6, all of which promote a pro-metastatic tumor microenvironment." (PMID 41139205, 2025). "Activated MCs release cytokines such as IL-6, TNF-α, and IL-13, which are known to promote transcriptional repression and DNA methylation at tumor suppressor loci via STAT3 and NF-κB signaling cascades." (PMID 40871387, 2025).
tumor (continued). "Lymphocytes inhibit apoptosis by secreting TNF alpha and interferon gamma and contribute to long-term survival by preventing tumor migration and invasion." (PMID 40282930, 2025). "Our current results tie these threads together, indicating that TNF-α elevations go hand-in-hand with increases in these key tumor markers." (PMID 40299527, 2025). "An elevated PCNA expression reflects increased proliferative activity in aggressive tumor phenotypes, while high TNF-α levels contribute to an inflammatory tumor microenvironment that facilitates cancer cell invasion and metastasis." (PMID 40430573, 2025). "Tumor- and host-derived cytokines (e.g., IL-6 family, TNF-α) increase receptor activator of nuclear factor-κ B ligand (RANKL) expression and inhibit osteoprotegerin (OPG), which drives remodeling toward osteoclastogenesis and cortical/trabecular loss." (PMID 40869331, 2025). "On 10x Genomics Visium data from a breast cancer sample, GASTON-Mix reveals spatial gradients of hypoxia and TNF-α signaling that are localized to specific tumor domains." (PMID 40662777, 2025). "The presence of tumor cells was sufficient to upregulate several other pro-inflammatory cytokines and chemokines, including tumor necrosis factor alpha, IL-6, chemokine C-C motif ligand 3 (CCL3), and CCL4, regardless of anti-PD-L1 treatment." (PMID 41050935, 2025). "In accordance with these diverse tumor ecosystems, regional TNF-α expression was strongly increased within the immune-rich ‘reactive’ subTME regions, which supports a BL inflammatory phenotypic state in PDAC patients." (PMID 39762215, 2025). "Pro-inflammatory cytokines such as IL-1β, IL-6, and TNF-α not only drive tumor progression and invasion but also contribute to chemotherapy resistance, underscoring their relevance as both biomarkers and therapeutic targets." (PMID 41155372, 2025). "This shift was associated with decreased pro-inflammatory cytokines (IL-1β, TNF-α) and increased anti-inflammatory cytokines (IL-10, IL-4), along with suppression of tumor-promoting pathways and improved intestinal barrier integrity." (PMID 40417220, 2025). "Experimental work has shown that sustained TNF-α signalling promotes DNA damage, angiogenesis, and tumour immune evasion via NF-κB and JAK/STAT pathways." (PMID 41473193, 2025). "A number of natural and synthetic compounds, including 17‐allylamino‐17‐demethoxygeldanamycin, parthenolide, wogonin, and luteolin have been shown to inhibit TNF‐α activated NF‐kB pathways, resulting in TNF‐α induced cytotoxicity of tumour cells." (PMID 39592417, 2025). "Eosinophils can enhance CD8 T cell recruitment and tumor cytotoxicity by promoting TNF-α and IFNγ signatures, potentially leading to prolonged overall survival, regardless of treatment type." (PMID 40386779, 2025). "LPS activates Toll-like receptor 4 (TLR4), leading to NF-κB activation and the subsequent transcription of inflammatory mediators such as IL-6 and TNF-α, thereby fostering chronic low-grade inflammation and tumour progression." (PMID 40647494, 2025). "TILT-123 intended to mimic the effect of lymphodepleting chemotherapy and high-dose IL-2 by the viral expression of TNF and IL-2 locally in the tumor." (PMID 40107242, 2025). "We propose a mechanistic model in which chronic cytokine signaling—particularly via IL-6, TGF-β, and TNF-α—drives a feedforward loop that reinforces tumor aggressiveness." (PMID 40933989, 2025). "Cytokines including CCL-2, IL-6, IL-8, IL-10, IL-13, and TNF-α show tumor-specific secretion profiles, with experimental evidence demonstrating TIC-derived cytokines mediate immune evasion through recruitment and activation of MDSCs and TAMs." (PMID 40777043, 2025).
tumor (continued). "TNF-α, a key pro-inflammatory cytokine in tumors, is constitutively overexpressed via its receptor on tumor cells, correlating with sustained NF-κB activation and elevated MCP-1/CCL2 expression." (PMID 41341593, 2025). "The core of this loop, driven by IL-6, TNF-α, and IL-8, directly promotes tumor cell survival, proliferation, and invasion, while also inducing angiogenesis, thereby facilitating tumor metastasis." (PMID 41394847, 2025). "Another possible explanation for the observed pro-tumor role of M1 macrophages is their ability to produce TNF-α, which several studies have identified to be a strong promoter of OSCC growth and invasion." (PMID 40724900, 2025). "Cytokines, such as CCL-2, IL-6, IL-8, IL-10, IL-13, and TNF-α, exhibit tumor-specific secretion profiles." (PMID 40777043, 2025). "When NF-κB is activated by stimuli such as TLR ligands, IL-1β, and TNF-α, it can directly induce macrophage differentiation into M1 phenotype of TAMs, which generally exerts tumour-suppressive effects." (PMID 40407951, 2025). "TNF‐α, a pro‐inflammatory cytokine involved in tumor progression and immune modulation, was markedly elevated in the ZGE + DOX group, followed by the ZGE and DOX groups, with minimal expression in Sham tissues." (PMID 41306344, 2025). "Nevertheless, TNF-α can exert pro-tumor effects by promoting tumor cell proliferation, survival, and angiogenesis." (PMID 40933989, 2025). "EAC tumor induction triggered a robust inflammatory response, significantly elevating plasma TNF-α (+ 104.1%), VEGF (+ 31.6%), and IL-6 (+ 169.4%) levels compared to normal controls (p < 0.05)." (PMID 41326498, 2025). "The influence of NF-κB extends beyond tumor cells: in cancer-associated fibroblasts (CAFs), radiation induces secretion of pro-inflammatory cytokines (e.g., IL-6, IL-1β, TNF-α) in an NF-κB-dependent manner, creating a supportive niche for tumor cell survival." (PMID 40725389, 2025). "Analysis of tumor tissues indicated that, compared to the control group, the concentrations of TNF‐α were significantly elevated in the CB group, AKK group, and CB‐AKK combined group, whereas the concentrations of IL‐6 and IL‐10 were significantly reduced." (PMID 40497373, 2025). "We assessed the production of IFN-γ and TNF-α by tumor-infiltrating CD8+ T cells and found a significantly greater proportion of IFN-γ+CD8+ T cells in tumors of Prkaa1/2fl/flFoxp3YFP–Cre mice." (PMID 40100289, 2025). "The concentrations of immune‐promoting Th1 cytokines (IFN‐γ, TNF‐α, and IL‐2) as well as proinflammatory signal (IL‐6) determined in culture supernatants and tumor tissues were evidently higher in N@VP + 2 Gy group." (PMID 40231790, 2025). "For instance, TNF-α levels exhibited a progressive increase from Tis through early to advanced-stage tumours (Spearman’s correlation, ρ = 0.32, p < 0.05)." (PMID 41465261, 2025). "As an extension, IFN-γ and TNF-α neutralization resulted in a reduction of CD4+Foxp3+ Tregs in the LLC tumor bed compared with IgG-treated mice." (PMID 40553564, 2025). "Researchers have found that certain intra-tumor microorganisms can affect the production and secretion of cytokines, such as IL-6 and TNF-α." (PMID 40475759, 2025). "In some contexts, TNF-α promotes chronic inflammation, which creates a tumor-friendly microenvironment." (PMID 40563999, 2025). "M1 macrophages secrete large amounts of various pro-inflammatory cytokines, such as TNF-α, IL-1β and inducible nitric oxide synthase, which have powerful pro-inflammatory and anti-tumor effects." (PMID 40070843, 2025). "Tumor-derived cues generally favor M2 polarization, resulting in the secretion of cytokines such as IL-4, IL-6, IL-1β, and TNFα." (PMID 40422235, 2025). "In early tumor stages, M1 macrophages exert anti-tumor effects through pro-inflammatory cytokine production, such as TNF-α and IL-1β, and antigen presentation, yet their functions are often compromised by immunosuppressive mechanisms within the TME." (PMID 41459510, 2025).